NOTCH3 (notch receptor 3)
Diseases named in the same sentence as NOTCH3 in open-access papers (continued):
Sharing a sentence is not in itself a finding about the gene and the disease.
tumor (continued). "A high ratio of CAFs to tumor cells in 3D cocultures leads to an increase in NOTCH3 expression in cocultures of both UT-SCC-24B and UT-SCC-42B cells." (PMID 38001580, 2023). "Mechanistically, we demonstrated that Notch3 prevents tumor initiation via HeyL-mediated inhibition of Mybl2, an important regulator of cell cycle." (PMID 36854682, 2023). "In patient-derived xenograft models of colorectal cancer and T-ALL, the expression of Notch ligand DLL4 in endothelial cells was reported to facilitate an escape from dormancy and metastatic colonization by activating Notch3 signaling in tumor cells." (PMID 37887354, 2023). "Mechanistically, IGF2BP3 activates Notch3 signaling by maintaining NOTCH3 mRNA stability in an m6A-dependent manner, thus enhancing the tumor-initiating ability of DTCs and promoting the development of metastasis." (PMID 37853162, 2023). "It was reported that JAG1 expression in the cytoplasm is correlated with the expression of NOTCH3 in tumor cells, suggesting an interaction between these two proteins." (PMID 37860822, 2023). "Through analysis of NPC tumor tissues and cellular models, we reported that enhancer remodeling activates NOTCH3 to confer chemo-resistance in NPC." (PMID 37563118, 2023). "In human tumor single-cell analysis, strong Notch3 expression is maintained in the stromal compartment." (PMID 36854682, 2023). "Notch1 and Notch3 signal transduction promotes tumor cell proliferation and inhibits apoptosis in certain NSCLC cell lines." (PMID 36644230, 2023). "Treatment with an anti-DLL4 neutralizing antibody or the silencing of Notch3 in tumor cells had marked pro-apoptotic, anti-proliferation, and reduced tumor burden in vivo." (PMID 37887354, 2023). "In this study, through transcriptomic profiling analysis of 23 tumor tissues, we found that NOTCH3 was aberrantly highly expressed in chemoresistance NPC patients, with NOTCH3 overexpression being positively associated with poor clinical outcome." (PMID 37563118, 2023). "There were significant differences in tumor volumes and weights between the control and the Notch3 knockdown mice." (PMID 35258176, 2022). "Jagged 1 in turn induces NOTCH1 and perhaps NOTCH3, forming a Jagged-involved tumor-stromal paracrine signaling loop." (PMID 36517618, 2022). "A recent report suggested that Notch3 is activated by Akt and regulates the tumor progression of mesenchymal colorectal cancer." (PMID 35931736, 2022). "This study conclusively established that differential ligand induction by the tumor microenvironmental cells leads to differential Notch3 activation in tumor cells in a homo- and heterotypic fashion." (PMID 35884426, 2022). "The overall mortality increased 1.2 times with each higher degree of NOTCH3 expression (p < 0.01) and 2.1 times (p < 0.001) with each higher tumor stage." (PMID 35073251, 2022). "Similar to the in vitro results, Notch3 knockdown effectively decreased the tumor volumes and weights." (PMID 35258176, 2022). "In PDAC, high levels of NOTCH3 expression were correlated with tumour grade, metastasis, tumour-node-metastasis (TNM) stage, and, hence, shortened patients survival time." (PMID 35954379, 2022). "Overexpression of NOTCH3 is related to cell hyperproliferation and apoptosis inhibition, as well as tumor metastasis and recurrence." (PMID 35332121, 2022). "Notch3 expression in tumor xenografts decreased in a dose-dependent manner in the BH treatment group compared with that in the model group, according to the IHC analysis." (PMID 35463301, 2022). "A particularly interesting potential interaction with high relevance for tumor biology includes JAG2 (cancer) with NOTCH3 (mouse stroma), and interactions of integrins (ITGA2, ITGA2B) with ECM proteins (COL2A1, LAMA1)." (PMID 35053442, 2022). "The expression of Delta-like 4 in the tumour microenvironment and increased NOTCH3 signalling in tumour cells are related to the escaped of human T-ALL cells from dormancy." (PMID 35681778, 2022).
tumor (continued). "NOTCH3 was recently verified as a prognostic factor in the regulation of biological activity, including tumor cell adhesion, migration, invasion, and survival." (PMID 36382054, 2022). "Notch3, a member of the Notch family of transmembrane receptors, is considered an oncogene or tumor suppressor in distinct cancers." (PMID 36139447, 2022). "After comparing the two models obtained, the predictive value of the number of relapses was higher for overall mortality, while NOTCH3 expression, tumor stage, and cancer divergent differentiation had greater value in predicting UBC-specific mortality." (PMID 35073251, 2022). "In this neoplasia, NOTCH3 promotes JAG1, a phenomena that is caused by a NOTCH3/JAG1 auto-sustaining loop." (PMID 35326610, 2022). "Overall, our results demonstrate that functional CD11b+Gr-1+ MDSCs are present in the tumor environment of Notch3-dependent T-ALL." (PMID 35444651, 2022). "In Western blotting and IHC analysis, BH significantly induced the expression of FOXO3a in tumor tissue, whereas BH downregulated the expression of FOXO3a upstream regulators (NOTCH3, β-catenin) and Bcl-2 downstream genes in tumor tissue." (PMID 35463301, 2022). "Previously, we have shown that the repression of NOTCH3 is one of the mechanisms of the tumor suppressive functions of CBFB and RUNX1." (PMID 33945523, 2021). "NOTCH3 activation also drives tumor growth and regulates stroma-mediated therapeutic resistance by expanding therapy-resistant tumor-initiating cells in BLBC." (PMID 34374886, 2021). "Several reports indicate that impairing the acetylation/deacetylation balance of Notch3 using HDAC inhibitors (HDACi) that favor hyperacetylation can negatively affect the stability and function of Notch3 in cancer cells and tumor xenograft mouse models." (PMID 34195229, 2021). "NOTCH3 was confirmed to be a direct target of two tumor suppressor microRNAs (miRNAs), namely miR-491-5p and miR-875-5p." (PMID 33452458, 2021). "Blocking Notch3 signaling in metastatic OC can inhibit the adhesion, migration and metastasis of tumor cells, while also enhancing their chemo-sensitivity." (PMID 34195229, 2021). "Mangiferin, a C-glucosyl xanthone (1,3,6,7-tetrahydroxy-xanthone-C2-β-D-glucoside), can specifically repress Notch3 signaling, which increases apoptosis and inhibits OC tumor growth both in vitro and in vivo." (PMID 34195229, 2021). "In T-ALL harboring Notch3 gain-of-function mutations, anti-Notch3 NRR mAbs show potent anti-leukemic activity in T-ALL cell lines and tumor xenografts." (PMID 34195229, 2021). "In NSCLC, chronic exposure to gemcitabine drastically upregulates Notch3 expression by tumor cells, whereas the addition of DAPT sensitized cell lines to the pyrimidine analogue, affecting pro- and anti-apoptotic protein expression patterns." (PMID 34680255, 2021). "In recent years, more and more attention has been paid to the role of Jagged1/Notch3 system in angiogenesis, particularly in tumour angiogenesis." (PMID 34291565, 2021). "While PTEN knockdown significantly reversed the inhibitory effect of Notch3 on tumor proliferation in the N3ICD + shPTEN model." (PMID 34006834, 2021). "Notch3 expression of cancer cells was negatively related to the tumor differentiation and prognosis." (PMID 35118116, 2021). "This indicates that the effects of Notch3 on tumor angiogenesis depend on the cellular context, such as the availability and amounts of Notch ligands in tumors." (PMID 34195229, 2021). "A monoclonal antibody OMP-59R5 that selectively targeting Notch2 and Notch3 can inhibit xenograft tumor growth." (PMID 34988077, 2021). "Most Notch3-targeting miRNAs are tumor-suppressive, and are downregulated in tumor tissues compared to normal tissues." (PMID 34195229, 2021). "In PTX-resistant OC, the decreased expression of the tumor-suppressive miRNAs miR-136 and miR-150 contributes to the overexpression of Notch3." (PMID 34195229, 2021).
tumor (continued). "To summarize, the activation of NOTCH3 in gastric carcinogenesis is partly due to the silence of tumor suppressor miRNAs, miR-491-5p, and miR-875-5p." (PMID 33452458, 2021). "In summary, mRNA expression in tissue or immunohistochemistry staining of NOTCH3 from primary tumor tissue are likely to be stable predictive methods for prognosis and response to chemotherapy in patients with advanced NSCLC." (PMID 34722241, 2021). "Notch3 signaling plays a critical role in tumor resistance to platinum, taxane, or their combination chemotherapy regimens, especially in OC." (PMID 34195229, 2021). "In pre-clinical experiments, Notch3-specific siRNAs or shRNAs were able to prevent Notch3 activation and potently inhibit tumor cell growth in vivo and in vitro." (PMID 34195229, 2021). "Genes in cluster 4 associated with cancer tissue (0.83) included many oncogenes: NOTCH3 signaling promotes tumor growth in CRC, whereas MMP14 and VEGFA are correlated with poor prognosis." (PMID 34458146, 2021). "Taken together, NOTCH3 is a functional target negatively regulated by tumor-suppressive miR-491-5p and miR-875-5p." (PMID 33452458, 2021). "Of note, Notch3-supported CSC activity is also involved in the mechanisms of tumor chemoresistance, as well as tumor metastasis and angiogenesis, indicating the key role of Notch3 signaling in cancer." (PMID 34195229, 2021). "In response to EGFR-TKI therapy of non-small-cell lung carcinoma (NSCLC), Notch3 physically binds to β-catenin in the cytoplasm of tumor cells to activate β-catenin signaling." (PMID 34195229, 2021). "Most DEGs in the brown module were involved in tumor progression or metastasis (module membership >0, cor = 0.83, p < 2.2e-16), including NOTCH3, VEGFA, SNAL1, TGFBR1, and MMP14, thereby confirming the correlation of some DEGs with phenotypes." (PMID 34458146, 2021). "The anti-Notch3 component binds the agent to Notch3-expressing tumour cells, where it is internalised and trafficked to vesicles containing proteolytic enzymes." (PMID 34295896, 2021). "In NSCLC and SCLC, NOTCH3 signaling acts as a tumor-promoting and -suppressing pathway, respectively." (PMID 34722241, 2021). "In TCGA-COAD datasets, NOTCH3 was highly expressed in tumor tissues compared to those of the normal group." (PMID 34733326, 2021). "Alternatively, ectopic expression of NOTCH3 in ECs was associated with both increased DLL4 expression and increased tumor angiogenesis in a murine xenograft model." (PMID 34043714, 2021). "In HCC chemotherapy, a well-tolerated combination of sorafenib and valproic acid was found to synergistically inhibit tumor growth by downregulating Notch3 and p-Akt." (PMID 34195229, 2021). "We provided the first evidence that NOTCH3 is negatively regulated by tumor-suppressive miRNAs, miR-491-5p, and miR-875-5p." (PMID 33452458, 2021). "Taken together, these data indicated that Notch3 expression is positively correlated with elevated PTEN expression and associated with a lower capacity of tumor proliferation and incidence of involved node status." (PMID 34006834, 2021). "Notch3 signaling promotes tumor angiogenesis in a canonical CSL-dependent manner, which requires cell-cell interactions and is driven by Notch ligands." (PMID 34195229, 2021). "The combination of EGFR-TKIs and a β-catenin inhibitor abrogates the Notch3-dependent activation of β-catenin, which strongly attenuates tumor onset, improving the OS and RFS of NSCLC xenograft mice." (PMID 34195229, 2021). "The knockdown of Notch3 using small interfering RNAincreased the platinum therapy response, demonstrating that tumor chemo-sensitivity modulation by GSI-I is Notch signaling specific." (PMID 33673088, 2021). "NOTCH3, as the central part of the cascade, promotes tumor progression through inhibition of apoptosis." (PMID 33452458, 2021). "This chimera exhibited a high Notch3 silencing efficiency in OC cell lines, as well as potent anti-tumor effects." (PMID 34195229, 2021).
tumor (continued). "In this case, inhibition of Notch3 has given rise to elevated tumor growth and to increased IL-6 expression by the tumor cells, which then caused CSC expansion." (PMID 32605277, 2020). "For example, in estrogen receptor-α positive tumour cells, Notch3 activity has been reported to suppress epithelial–mesenchymal transition and reduce metastases." (PMID 32210034, 2020). "CEBPB accumulation in NRF2-activated NSCLCs is found to be one of the prerequisites for the establishment of the unique enhancers, in which NOTCH3 enhancer is critical for the promotion of tumor-initiating activity." (PMID 33219226, 2020). "RNA‐seq analysis revealed the tumor over‐expressed several genes compared to normal tissue, including components of the Notch signaling pathway, NOTCH3 and JAG1." (PMID 32652895, 2020). "Elevated accumulation of CEBPB in NRF2-activated NSCLCs is found to be one of the prerequisites for establishment of the unique NRF2-dependent enhancers, among which the NOTCH3 enhancer is shown to be critical for promotion of tumor-initiating activity." (PMID 33219226, 2020). "To further verify that the NOTCH3 enhancer promotes the tumor-initiating activity of NRF2-activated NSCLC cells, we conducted a serial transplantation assay and compared the frequency of tumorigenesis." (PMID 33219226, 2020). "The result of immunohistochemistry revealed that after the inhibition of SNHG3 expression, Notch1-, Notch2- and Notch3-positive cells in MCF-7 xenograft tumor increased (p < 0.05)." (PMID 32883233, 2020). "In this study, we explored unique NRF2 target genes and identified NOTCH3 as a key regulator of the tumor-initiating activity in NRF2-activated NSCLCs." (PMID 33219226, 2020). "C-terminal truncations of Notch3, associated with increased stability of the Notch3 ICD, have also been identified in tumours with high Notch3 expression." (PMID 32210034, 2020). "We next conducted xenograft experiments to examine the in vivo contribution of the NOTCH3 enhancer to the promotion of tumor-initiating activity in NRF2-activated NSCLC cells." (PMID 33219226, 2020). "Previously, it’s reported that tumor-bearing mice treated with fulvestrant exhibited enriched self-renewing CD133hi cancer stem cells, in which Notch3 and mRNA transcripts of Notch signaling pathway were elevated." (PMID 33324567, 2020). "NOTCH3-KO (PE04-NOTCH3-KO cells 5 × 106 cell/mouse; i.p. injected) greatly reduced tumorigenesis by extending mouse survival to 161 ± 21 days, with tumor numbers and ascites volumes significantly lower than the control mice." (PMID 33316986, 2020). "Western blot analysis of mouse tumour tissue from the nude mouse model of tumorigenesis revealed that overexpression of circ_PUM1 increased NOTCH3 levels in vivo." (PMID 32073729, 2020). "The tumor growth of NOTCH3 enhancer-disrupted cells, ΔN3U H460, ΔN3U A549, and ΔN3U H2023, was decreased compared with that of their parental cells." (PMID 33219226, 2020). "Selective Notch3 inhibition impairs tumor growth, whereas Notch3 agonism correlates with a malignant phenotype and increased proliferation." (PMID 31379945, 2019). "NOTCH3 expression in tumor tissue of the low (<50%) subgroup was lower compared with normal pancreas in the high (>50%) subgroup." (PMID 31652721, 2019). "Our results confirmed an overall increase in expression of NOTCH3 and miR-21 in tumor tissue when compared with normal pancreas." (PMID 31652721, 2019). "In summary, NOTCH3 repression contributes to the tumor suppressive function of the nuclear CBFB/RUNX1 complex." (PMID 31061501, 2019). "When analyzing medians of NOTCH3 and miR-21 expression, both were significantly increased in tumor tissue: upregulation was observed in 72.3% (47/65) and 95.4% (62/65) of patients, respectively." (PMID 31652721, 2019). "According to western blot analysis, Notch3 showed lower expression levels in those tumor cell lines with relatively high malignancy, such as MDA-MB-231 and BT549 TNBC." (PMID 31096822, 2019).
tumor (continued). "Notch‐3 is a member of the Notch family of receptors and plays both oncogenic and tumor suppressor role in malignant tumors." (PMID 30873760, 2019). "Gene expression of selected markers ENT1, NOTCH3, and miR-21 was determined in both tumor and normal tissue." (PMID 31652721, 2019). "To further study the role of Notch3 and its ligand Jag1 in EC-tumor interaction, we silenced Jag1 expression on E4+ECs using siRNA and showed an inhibition of APOCC or OVCAR3 proliferation in co-cultures with E4+ECssiJag1." (PMID 31182109, 2019). "Multiple studies have demonstrated that specific Notch3 inhibition sensitizes tumor cells to chemotherapy in drug-resistant OC, with an efficacy comparable to GSIs." (PMID 30723507, 2019). "Contrastingly, other studies have reported that FAM172A was a tumor-suppressor gene which mediated cell cycle arrest at least partially, by upregulated expression of the Notch 3 pathway." (PMID 31915594, 2019). "NOTCH3 showed significant upregulation in tumor tissue of the low (<50%) subgroup specimens only, and the amount of miR-21 was increased in both tested subgroups." (PMID 31652721, 2019). "Further investigation is, however, needed, because there is the possibility that the expression of ENT1 and/or NOTCH3 in normal pancreas was influenced by factors produced by the tumor." (PMID 31652721, 2019). "Next-generation sequencing revealed loss of heterozygosity with very high allelic frequency in NOTCH3, TGFB1, EZH2 and KMT2C in the patient tumor, the subcutaneous PDX and the PDOX." (PMID 31732509, 2019). "The acquisition of a “stemness phenotype” through a Notch3-dependent mechanism suggests a link between Notch3 activation and drug resistance, and therefore tumor recurrence, as stem cell-like properties are known to be involved in chemoresistance development." (PMID 30723507, 2019). "Based on preclinical and phase Ib results suggesting a positive correlation between Notch3 gene expression and tarextumab anti‐tumor activity, patients were also divided into subgroups of low, intermediate, and high Notch3 gene expression." (PMID 31347292, 2019). "Among the upregulated genes in the tumors compared to those in the normal tissue, we found CKAP4, DUSP1, PAX8, AP1M2, C-KIT and NOTCH3, with NOTCH3 being the only gene that was upregulated in all tumor types." (PMID 31159852, 2019). "To investigate possible association of ENT1, NOTCH3, and miR-21 levels with patients’ DSS, we quantified gene expression of the transcripts in tumor tissue microdissected from FFPE samples (n = 69)." (PMID 31652721, 2019). "We found that Notch3-silenced tumours have significant lower levels of Aco1, Idh1 and Mdh1 than control counterparts." (PMID 30765875, 2019). "A possible role of the Notch pathway in MCC was investigated by monitoring the levels of Notch1, Notch2, Notch3, and Jagged 1 in MCPyV-negative and positive tumours." (PMID 31408949, 2019). "Inhibition of NOTCH3 using some small molecular inhibitors can restrain tumor growth and induce cell apoptosis." (PMID 29765324, 2018). "In oral squamous cell carcinomas, Notch3 signaling is activated in stromal fibroblasts, in turn eliciting tumor angiogenesis." (PMID 29462871, 2018). "All four NOTCH receptors are expressed in these tumor propagating cells, but among them NOTCH3 is the receptor more relevant from a functional point of view." (PMID 30060526, 2018). "In turn, IL-6 increases the expression of Jagged1 and Notch3 in tumor cells and stimulates tumor growth and drug resistance." (PMID 30154786, 2018). "We performed IHC analysis of Notch3 and β-catenin on a total of three paired tumor samples obtained prior to the start of erlotinib treatment and at the time of progression." (PMID 30097569, 2018). "Results showed that EVO potently reduced tumor size and tumor numbers in mice, and inhibited NOTCH3 in the tumors." (PMID 29765324, 2018).